MTOR (mechanistic target of rapamycin kinase)
Diseases named in the same sentence as MTOR in open-access papers (continued):
Sharing a sentence is not in itself a finding about the gene and the disease.
lung cancer (continued). "Pathway analyses suggest that cell proliferation and oncogenic signaling pathways, including mTOR, are enriched with short transcript isoforms in lung cancer." (PMID 34556645, 2021). "It is reported that curcumin and apigenin suppress cell migration and invasion by modulating the PI3K/Akt/mTOR signaling pathway in human glioblastoma cells and in a lung cancer model respectively." (PMID 34858179, 2021). "In conclusion, these results indicated that the overexpressed GTSE1 was involved in the progress of lung cancer by promoting proliferation migration and invasion and inhibiting apoptosis of lung cancer cells via activating AKT/mTOR signaling." (PMID 34007784, 2021). "Currently, more and more mTOR inhibitors have been applied in the clinical treatment of malignancies, such as lung cancer, laryngeal cancer, and pancreatic cancer." (PMID 34874800, 2021). "The current review will focus on the role of the PI3K/AKT/mTOR pathway in lung cancer aggressiveness and promising drugs/natural compounds targeting this signaling pathway that are undergoing clinical or preclinical trials." (PMID 34279440, 2021). "In vitro studies in A549 lung cancer cell lines have shown that FUT7 overexpression augments sLeX synthesis to trigger cell proliferation via the activation of the EGFR/AKT/mTOR signaling pathway." (PMID 33963380, 2021). "The QYSL formula has anti-lung cancer effects and promotes autophagy through the mTOR signaling pathway." (PMID 34093717, 2021). "A recent study reported that ENO1 promoted the self-renewal and malignant phenotype of lung cancer stem cells by affecting the AMPK/mTOR pathway." (PMID 34627260, 2021). "The in vivo studies also further confirmed the downregulation of the PI3K/Akt/mTOR (mechanistic target of rapamycin) pathway and downstream effectors, as well as a more profound perturbation of pH homeostasis in lung cancers under exposure to AZ+SFN treatment." (PMID 34948200, 2021). "mTOR acts in a synergistic manner to inhibit tumor growth in mouse prostate and lung cancer models, and phosphorylated or activated mTOR is found in 74% of the NSCLCs, making it an additional target for NSCLC therapy." (PMID 34178945, 2021). "The hyperactivity or overexpression of some groups of proteins, such as the PI3K/AKT/mTOR and Bcl-2 family proteins, can be found in lung cancer." (PMID 33805467, 2021). "Currently, PI3K/AKT/mTOR signaling has been reported as an emerging source of lung cancer aggressiveness." (PMID 34279440, 2021). "One study demonstrated that treatment with mTOR kinase inhibitors resulted in elevated expression levels of cleaved caspase 3 proteins and dramatically downregulated Bcl-2 levels when mTOR was downregulated in human laryngocarcinoma and lung cancer." (PMID 33925400, 2021). "Restoration of piR-55490 suppressed cell proliferation in lung cancer by suppressing Akt/mTOR pathway." (PMID 34295823, 2021). "The following sections describe the recent research and development of natural compounds targeting the PI3K/AKT/mTOR signaling pathway in lung cancer, particularly new natural compounds that are currently in the preclinical stages of development." (PMID 34279440, 2021). "Preclinical investigation of several natural products targeting the PI3K/AKT/mTOR signaling pathway in lung cancer." (PMID 34279440, 2021). "For example, upregulation of LINC00963 can inhibit ubiquitination of PGK1 to activate the AKT/mTOR pathway, thus promoting the metastasis of lung cancer, and DLX6-AS1 promotes tumor proliferation by regulating the JAK/STAT pathway." (PMID 33981850, 2021). "ETD exhibits an inhibitory effect on lung cancer cell migration and invasion via inhibition of Akt/mTOR signaling, and thereby modulates actin reorganization and downregulates MMP expressions." (PMID 33758209, 2021).
lung cancer (continued). "The first mechanism involves enhanced GSK3β/β-TrCP-dependent degradation of NRF2 through activation of the AMPK/mTOR signaling pathway, and thereby triggering ferroptosis selectively in lung cancer cells." (PMID 34093872, 2021). "In parallel to oxidative stress, oncogenic mutations in lung cancer can also induce HIF activation, e.g., phosphatase and tensin homolog (PTEN), PI3K/Akt/mTOR pathway, or epigenetic alterations." (PMID 35070990, 2021). "Our findings also demonstrate that ETD significantly decreased Akt phosphorylation and activation of its downstream molecules mTOR and p70S6K, leading to the suppression of lung cancer cell migration." (PMID 33758209, 2021). "Mammalian target of rapamycin (mTOR) is one of the most commonly activated pathways in human cancers, including lung cancer." (PMID 34421360, 2021). "Curcumin was shown to inhibit epithelial–mesenchymal transition (EMT) and angiogenesis in HGF-induced lung cancer cells by regulating c-Met-dependent PI3K/Akt/mTOR signaling pathways." (PMID 34299042, 2021). "A study have shown that Shenmai injection can reprogram glucose metabolism and enhance the sensitivity of lung cancer cells to chemotherapy drugs through the AKT/mTOR/c-Myc pathway." (PMID 34552496, 2021). "lncRNA DANCR was found to be involved in the progression of lung cancer through sponging miR-496 and then regulating the level of mTOR." (PMID 34514167, 2021). "From the biomarkers associated with brain metastasis of lung cancer, we discover a significant enrichment of PI3K-pathway aberration and verify using our pharmacogenomic database that targeting MTOR is highly effective in treating lung cancer brain metastasis." (PMID 34795255, 2021). "A previous study has also reported that delicaflavone exhibited favourable anticancer properties with anti-lung cancer effects in vitro and in vivo by inducing autophagic cell death via the Akt/mTOR/p70S6K signalling pathway." (PMID 33849505, 2021). "miR-206 inhibited HGF-induced epithelial-mesenchymal transition (EMT) and angiogenesis in lung cancer, by suppressing Met/PI3k/Akt/mTOR signaling." (PMID 34956857, 2021). "More importantly, autophagy (cytoprotective autophagy) inhibition has been recently reported to enhance the anti-tumor effects of UA on lung cancer cells by the mTOR." (PMID 34512368, 2021). "Erianthridin suppresses the metastatic behavior of A549 and H460 lung cancer cells through the AKT/mTOR pathway." (PMID 34279440, 2021). "Bergamottin, a naturally occurring furanocoumarin, suppressed the metastasis of lung cancer cells through inhibiting the TGF-mediated EMT process by blocking the activation of PI3K/Akt/mTOR signaling." (PMID 34354794, 2021). "For example, Skullcapflavone I, a flavone compound extracted from Huangqin, has been demonstrated to exert anti-cancer effect on lung cancer cells through inactivating PI3K/AKT/mTOR signaling pathway." (PMID 33558586, 2021). "In conclusion, we defined high GTSE1 expression as a worse prognostic trigger for lung cancer patients and reported that GTSE1 acts as an oncogene by activating AKT/mTOR signaling in the lung cancer." (PMID 34007784, 2021). "Intriguingly, silenced piR-55490 promotes the growth of lung cancer by binding to the mTOR 3′UTR and activating the AKT/mTOR pathway." (PMID 34118972, 2021). "In human ovarian cells, lung cancer cells and human melanoma cells, curcumin inhibits the Akt/mTOR/p70S6K pathway to induce protective autophagy." (PMID 34512368, 2021). "A switch to a mechanistic target of rapamycin [mTOR]-inhibitor was performed in over half of patients after diagnosis of post-transplant lung cancer (24 of 41 [58.5%])." (PMID 34947875, 2021). "For example, in lung cancer cells piR-55490 was demonstrated to bind with 3′UTR of mTOR mRNA and induce its degradation." (PMID 34295823, 2021).
lung cancer (continued). "For instance, it has been documented that miR-499a-5p facilitates metastasis of lung cancer cells via upregulation of mammalian target of rapamycin (mTOR), and subsequent stimulation of EMT." (PMID 32784711, 2020). "Other reports also showed that p38 activated mTOR following oxidative stress in the human lung cancer cell line." (PMID 33249542, 2020). "Applying dioscin to A549 and H1299 lung cancer cells causes a dose-dependent increase in Erk1/2 and JNK1/2 activities, while reducing PI3K expression and Akt and mTOR phosphorylation." (PMID 32792945, 2020). "Another experimental study showed that a combination of B-cell lymphoma 2 (Bcl-2) and mTOR inhibition led to increased radiosensitization in a lung cancer models." (PMID 32668776, 2020). "Because miR-1911-3p negatively regulated mEAK-7 expression and subsequent mTOR signaling, lung cancer cell proliferation and migration were analyzed in response to miR-1911-3p." (PMID 33364499, 2020). "We have proposed a model about the regulation of PD-L1 on lung cancer growth by activating Akt/mTOR and Erk pathway." (PMID 32632098, 2020). "According to our study, baicalin was proved for the first time to inhibit the Akt/mTOR pathway, which mainly contributed to the cell arrest and survival inhibition, for its employment in lung cancer treatment." (PMID 33585556, 2020). "Inhibition of the overactivated Akt/mTOR pathway is likely an opportunity in the treatment of lung cancer." (PMID 30734151, 2020). "PI3K/Akt/mTOR signaling pathway is one of the major signaling cascades which is frequently activated in various human cancers including lung cancer." (PMID 32655659, 2020). "The most dominant signaling pathways activated in lung cancer are the PI3K/AKT/mTOR and the MAPK pathways." (PMID 33092114, 2020). "To determine the role of mTOR‐mediated autophagy inhibition in the LA‐induced suppression of lung cancer cell viability, we used Rap, a widely used mTOR‐selective inhibitor, in the experiments." (PMID 32090494, 2020). "Altogether, our data suggest that LA suppressed lung cancer cell viability through inhibition of autophagy in an mTOR‐dependent manner." (PMID 32090494, 2020). "We have previously prepared a methanol-based extract of rosemary leaves in our lab and when tested in lung cancer cells, we found a significant inhibition of proliferation and survival as well as an inhibition of Akt, mTOR, and p70S6K." (PMID 32012648, 2020). "Phosphoinositide 3-kinase (PI3K)/mechanistic target of rapamycin (mTOR) inhibitor BEZ235 showed an obvious anti-lung-cancer effect either as a support of chemotherapy or targeted therapy, or as a monotherapy." (PMID 32969473, 2020). "Evidence has shown that inhibition of the mTOR pathway represents a promising therapeutic approach for lung cancer." (PMID 31988639, 2020). "Molecular analysis revealed that the anti‐lung cancer effects of LA were mediated through promoting the mTOR‐mediated inhibition of autophagy." (PMID 32090494, 2020). "Previous review described that dysregulation of the Akt/mTOR signaling pathway was closely related to the tumor development, metastasis and apoptosis in lung cancer." (PMID 32913468, 2020). "We found that NiPT causes the ER stress response of lung cancer cells, leading to instability in the amount of intracellular energy, resulting in the activation of AMPK as well as the dephosphorylation of the mTOR, the autophagy suppressor." (PMID 32292717, 2020). "Similar to what miRNAs do, piR-55490 decreases the decay of mTOR mRNA through binding to its 3′ UTR; thus, inhibiting Akt/mTOR signaling in lung cancer cells." (PMID 32211149, 2020).
lung cancer (continued). "The natural compound delicaflavone can induce autophagy via the Akt/mTOR/p70S6K pathway in human lung cancer cells." (PMID 33187244, 2020). "Perifosine induces the degradation of key proteins in the mTOR axis through a GSK3/FBXW7-dependent mechanism in human lung cancer cells." (PMID 32577098, 2020). "Previous studies have revealed that rapamycin can increase the radiation sensitivity of lung cancer cells by inhibiting mTOR, and PI3K/mTOR inhibitor NVP-BEZ235 can enhance the radiosensitivity of human glioma stem cells." (PMID 33336000, 2020). "The potential therapeutic targets of bufalin included MDM2, PIK3CA, MAPK14, and MTOR, which can induce cell death through various mechanisms and exert anticancer properties against lung cancer, liver cancer, and other tumors." (PMID 32148531, 2020). "Signal transduction crosstalk between AR and EGFR often leads to p38MAPK-dependent activation of mTOR and cyclinD1 expression in prostate cancer cells and in lung cancer cells." (PMID 32929340, 2020). "Phosphorylation of IRS1S1101 increased in ZNF322A-silenced H1299 lung cancer cells which suggests ZNF322A is a regulator for IRS1/AKT/mTOR signaling pathway in NSCLC." (PMID 32576196, 2020). "MicroRNA-1911-3p; mEAK-7; mTOR signaling; Lung cancer; Cell proliferation; Cell migration; Cell biology; Gene expression; Gene regulation; Cancer research; Oncology." (PMID 33364499, 2020). "Confirming our observations from cell culture and mouse models, mTOR upregulation has previously been observed in Kras-mutant lung cancer patients that have relapsed following platinum-based chemotherapy." (PMID 32943635, 2020). "AKT/mTOR signaling pathway is a common signaling pathway, participating in the development of lung cancer." (PMID 33817257, 2020). "Collectively, we proposed glucose starvation and UPR in siZNF322A lung cancer cells altered mTOR signaling pathway and further induced autophagosome formation." (PMID 32576196, 2020). "Cucurbitacin I was also able to induce pro-death autophagy signalling in lung carcinoma cells through ERK/mTOR/STAT3 signalling by inhibiting ERK activation and the downstream phosphorylation of mTOR and STAT3." (PMID 32731620, 2020). "Our results pinpoint a rational and readily translatable strategy that combines mTOR inhibitors with standard chemotherapy to treat KRAS-mutant lung cancer." (PMID 31612108, 2019). "Cisplatin sensitivity is enhanced by co-treatment with mTOR inhibitors in various other cancers, including ovarian cancer, lung cancer, and osteosarcoma, as well as cervical cancer." (PMID 31387554, 2019). "We recently found that activation of mTOR signaling mediates a key resistance mechanism to chemotherapy in KRAS-mutant lung cancer." (PMID 31612108, 2019). "PI3K/mTOR/Akt is one of the most commonly genetically altered and deregulated oncogenic signaling pathways in cancer, including lung cancer and especially NSCLC." (PMID 31404976, 2019). "In this study, we reported that EA induced autophagy in lung cancer cells, with decreases in p‐Akt, p‐mTOR, and p‐P70S6K." (PMID 30353639, 2019). "Previous work has shown that FDG uptake by lung cancer cells is regulated by hypoxia, angiogenesis, glucose metabolism, and mammalian target of rapamycin (mTOR) signalling." (PMID 31527660, 2019). "Mounting evidence imply that the PI3K/Akt/mTOR pathway plays a crucial role in oncogenesis and is often reported to be activated in lung cancer." (PMID 31817720, 2019). "The phosphoinositide 3-kinase (PI3K)/AKT/mechanistic target of rapamycin (mTOR) signaling has been shown to contribute to tumorigenesis, tumor progression, and resistance to therapy in most human cancer types, including lung cancer." (PMID 31262325, 2019). "mTOR inhibition has been reported to suppress tumor growth in lung cancer cells and patient-derived xenograft (PDX) models." (PMID 31801598, 2019).
lung cancer (continued). "Previous research indicates that activation of the Akt/mTOR pathway promotes immune escape by driving PD-L1 expression in lung cancer." (PMID 31341011, 2019). "Taken together, all these data propose that FBXO22 accelerates lung cancer cell growth through inhibiting LKB1/AMPK/mTOR signaling." (PMID 31217475, 2019). "IARS2 knockdown reduced AKT Ser473 and Thr308 and MTOR phosphorylation levels in lung cancer A549 and H1299 cells." (PMID 31157169, 2019). "In our study, Ori induced AMPK/Akt/mTOR-dependent autophagosome accumulation, which further activated apoptosis to inhibit lung cancer cell growth and increase cisplatin sensitivity." (PMID 31475112, 2019). "FIP-gmi induces autophagy through the Akt-mTOR-p70S6K pathway, thereby inhibiting multidrug-resistant lung cancer cells." (PMID 31661772, 2019). "Our results suggest that BEZ235, an oral, dual PI3K/mTOR inhibitor, offers a new avenue for the therapeutics of lung cancer." (PMID 31262325, 2019). "Aspirin-triggered RvD1 (10 ng/mL) can block TGF-1-induced EMT of A549 lung cancer cells via suppression of the mTOR pathway by reducing the expression of pyruvate kinase M2." (PMID 31766574, 2019). "For example, the inhibition of the PI3K/AKT/mTOR pathway by apigenin was described in several cancers, including prostate cancer, lung cancer and hepatocellular carcinoma." (PMID 30678243, 2019). "In summary, our study shows that FBXO22 mediates K63-linked polyubiquitination of LKB1, thereby suppresses LKB1 activity and promotes lung cancer cell growth through LKB1/AMPK/mTOR pathway." (PMID 31217475, 2019). "mTOR pathway members and eIFs are overexpressed in malignancies, such as squamous cell carcinoma of the head and neck, cancer of the lung, thyroid, breast and other cancer types." (PMID 31586263, 2019). "In conclusion, these results demonstrated that regulation of Akt/mTOR pathway is closely related to autophagy induced by anlotinib in lung cancer cells." (PMID 30755242, 2019). "Beside, Hsp90 has been reported to interact with AKT to induce autophagy through activation of the AKT/mTOR pathway in lung cancer." (PMID 30305727, 2019). "Further, knockout of TIPE2 resulted in significantly reduced proliferation, survival, and migration of human lung cancer cells through modulation of the Akt/mTOR/NF-κB signaling axis." (PMID 31817720, 2019). "So in our study, we aimed to explore the role and correlation of autophagy, apoptosis and AMPK/Akt/mTOR induced by Ori in cisplatin-treated A549 cells, and provided a new therapeutic target against carcinogenesis and cisplatin resistance in lung cancer." (PMID 31475112, 2019). "DDR1 is an up-stream regulator of the AKT/mTOR pathway, a pathway involved in chemo-resistance in multiple cancers, including lung cancer." (PMID 31142317, 2019). "Ginkgolic acid (100 μM) can inhibit TGF-1-induced EMT of lung cancer cells through PI3K/AKT/mTOR inactivation." (PMID 31766574, 2019). "It has been reported that the radiation-activated PI3K/Akt/mTOR signaling pathway upregulates VEGF-C overexpression in lung cancer cells promoting endothelial cell proliferation." (PMID 31426614, 2019). "We report here that BGM can significantly inhibit TGF-β-induced EMT and invasive capability of lung cancer cells, and the mechanism underlying these effects can correlate to its ability to abrogate the activation of PI3K/Akt/mTOR kinases." (PMID 30004418, 2018). "The PI3K/AKT/mTOR signaling pathway is involved in the antitumor effects of ginsenoside Rg3 in lung cancer cells." (PMID 30116194, 2018). "Autophagy induction via AKT or mTOR inhibitors also leads to radiosensitization in lung cancer and glioma." (PMID 29679028, 2018). "We found that lung cancer PC14PE6/AS2 (AS2) had higher mTOR and Akt and also lower PTEN expression than A549 cells." (PMID 30245856, 2018).